IGF2BP1 (insulin like growth factor 2 mRNA binding protein 1)
Diseases named in the same sentence as IGF2BP1 in open-access papers (continued):
Sharing a sentence is not in itself a finding about the gene and the disease.
tumor (continued). "IGF2BP1 (insulin-like growth factor 2 mRNA binding protein 1) plays significant roles in carcinogenesis, including tumor cell proliferation and growth, invasion, and chemoresistance, and is associated with poor overall survival and metastasis in various types of human cancers." (PMID 35722625, 2022). "However, after adjusted to age, molecular classification, grade, tumor size, lymph node status, endocrine treated, and chemotherapy treated, only YTHDC1, FMR1, IGF2BP1 and WTAP showed a significant association." (PMID 34141492, 2021). "Therefore, the enhanced gene expression of SRF/IGF2BP1 is the driving factor of tumorigenesis and promotes tumour growth and metastasis." (PMID 34794452, 2021). "This suggests that IGF2BP1 regulates multiple, targeted genes and may influence tumor progression by regulating multiple mRNAs through m6A modification." (PMID 33391523, 2021). "Next, we explored whether lncRNA KB-1980E6.3/IGF2BP1/c-Myc complex could contribute to BCSCs-derived tumor initiation and tumor growth in vivo." (PMID 33469161, 2021). "Silencing IGF2BP1 reduces cell proliferation and promotes apoptosis in hepatocarcinoma cells, suggesting that miR-372 may act as a tumor suppressor by inhibiting IGF2BP1." (PMID 34575133, 2021). "Notably, 179 of 238 (75%) downregulated genes showed positive correlation with IGF2BP1 in at least 20 tumor cohorts." (PMID 33829040, 2021). "Furthermore, other studies have suggested that IGF2BP1 is a direct target of Wnt/β-catenin signalling and plays a crucial part in the progression of tumours." (PMID 34794452, 2021). "Remarkably, in one tumor we detected a breakpoint at the IGF2BP1 locus (sample #5)." (PMID 32719445, 2021). "However, a few recent studies found that suppressive roles for IGF2BP1 in tumor growth and metastasis in breast cancer and colon cancer." (PMID 34779401, 2021). "IGF2BP1 overexpression significantly affected tumor growth in subcutaneous xenograft models." (PMID 33051595, 2021). "Grossly, IGF2BP1 was overexpressed in tumor parts comparing to normal specimens (p-value = 0.045)." (PMID 34203267, 2021). "The IGF2 mRNA-binding protein 1 (IGF2BP1) is a non-catalytic post-transcriptional enhancer of tumor growth upregulated and associated with adverse prognosis in solid cancers." (PMID 32761127, 2020). "First, IGF2BP1 (insulin-like growth factor 2 mRNA binding protein 1) plays significant roles in carcinogenesis, including tumor cell proliferation and growth, invasion, and chemoresistance, and is associated with poor overall survival and metastasis in various types of human cancers." (PMID 33033522, 2020). "Thus, our findings reveal an undescribed mechanism by which MSI1 promotes tumor cell stemness and highlight the pivotal role of oncofetal RBPs like IGF2BP1 and MSI1 in promoting a stem-like tumor cell phenotype by antagonizing miRNA-dependent regulation." (PMID 33291443, 2020). "However, if BTYNB also interferes with other, conserved effector pathways of IGF2BP1 in cancer cells and impacts tumor growth remained largely elusive." (PMID 32761127, 2020). "In consequence, IGF2BP1 promotes tumor cell proliferation in vitro and tumor growth in vivo." (PMID 32761127, 2020). "Despite consistent stimulation of tumor cell proliferation and tumor growth by IGF2BP1, conserved effector pathways remained unknown." (PMID 32761127, 2020). "In addition, IGF2BP1 is overexpressed in primary tumor tissues such as breast cancer, colon cancer and non-small cell lung cancer." (PMID 32653017, 2020). "Besides, IGF2BP1 is a biofunctional target of miRNA and responsible for suppression on tumor growth and metastasis in cervical cancer." (PMID 31427725, 2019). "Therefore, the conservation of IGF2BP1-dependent regulation of SRF expression was analyzed in a panel of four tumor cell lines derived from distinct primary cancers." (PMID 30371874, 2019).
tumor (continued). "Finally, downregulated SRF synthesis upon IGF2BP1 deletion was also observed in ES-2-derived Xenograft tumors in nude mice (tumor samples were obtained from)." (PMID 30371874, 2019). "Total S6K1 and IGF2BP1 expression was unaffected by Lnc-THOR silencing or KO in tumor lysates." (PMID 31727877, 2019). "However, the increased RGS4 expression enhanced by IGF2BP1 depresses tumor cell migration and invasion." (PMID 29954406, 2018). "IGF2BP1 has both tumor-driving and tumor-suppressive roles in cancers in a context-based manner." (PMID 29954406, 2018). "Even though most of the presently found cancer-related mRNA targets of IGF2BP1 have been identified to promote tumor proliferation and growth, migration, and invasion, some mRNAs have been indicated to at least indirectly suppress tumor growth and metastasis." (PMID 29954406, 2018). "By stabilizing c-MYC and MKI67 transcripts, IGF2BP1 enhances tumor cell proliferation and growth." (PMID 29954406, 2018). "IGF2BP1 is broadly and highly expressed in embryonic and tumor tissues." (PMID 29954406, 2018). "IGF2BP1 serves as a post-transcriptional fine-tuner regulating the expression of some essential mRNA targets required for the control of tumor cell proliferation and growth, invasion, and chemo-resistance, associating with a poor overall survival and metastasis in various types of human cancers." (PMID 29954406, 2018). "Similarly, the miRNAs in tumors target the 3′-UTR of IGF2BP1, by which they regulate the expression of IGF2BP1-downstream targets and affect tumor cell proliferation, migration and invasion, and growth." (PMID 29954406, 2018). "However, different from the oncogenic role in previous colorectal tumors and cells, and other cancers, IGF2BP1 was demonstrated to have tumor-suppressive roles." (PMID 29954406, 2018). "Additionally, some ncRNAs were found to involve the regulation of tumor events by targeting IGF2BP1." (PMID 29954406, 2018). "A recent report shows that miRNA-142-5p could regulate the expression of IGF2BP3, which is strongly associated with an advanced tumor stage and is a predictor of poor prognosis among patients with HCC, as with IGF2BP1." (PMID 28302149, 2017). "However, the subsequent inhibition assays, luciferase reporter assay, and rescue assays further demonstrated that miR-140-5p exerts its tumor suppressor role in CC cells by targeting IGF2BP1." (PMID 27588393, 2016). "Our findings described a novel role of miR-140-5p as a tumor suppressor by targeting IGF2BP1 in CC." (PMID 27588393, 2016). "Interestingly, we found that H19/hsa-let-7b/IGF2BP1 competing triplet involved in the tumor state ceRNA network of UCEC." (PMID 27580177, 2016). "In HCC, IGF2BP1 could promote tumor cells proliferation by enhancing the expression of c-Myc, Ki-67 or PTEN/HSP27." (PMID 26547929, 2015). "In addition, several reports have described that IGF2BP1 promotes tumor cell proliferation by enhancing the expression of c-myc." (PMID 25889892, 2015). "This supports previous reports, suggesting a role of IGF2BP1 in tumor cell dissemination." (PMID 23677615, 2013). "In contrast, IGF2BP1-dependent sustainment of mesenchymal cell properties could be validated for all so far analyzed mesenchymal-like tumor-derived cells expressing IGF2BP1." (PMID 23677615, 2013). "Notably, IGF2BP3 knockdown in K562 cells (chronic myeloid leukemia) does not induce apoptosis by itself, an observation we can also confirm for IGF2BP1 in tumor cells derived from gastrointestinal cancers (unpublished)." (PMID 23069990, 2013). "Whether LEF1 or SNAI2 could recover IGF2BP1 knockdown-induced impairment of tumor cell migration was determined by their stable expression in IGF2BP1-depleted cells." (PMID 23677615, 2013). "In addition to controlling actin dynamics, IGF2BP1 sustains mesenchymal cell properties and modulates tumor cell migration also through the upregulation of LEF1 and SNAI2." (PMID 23677615, 2013).
tumor (continued). "Hence, although FN1 and CDH1 are presumably not the key markers involved, these findings supported the view that the role of IGF2BP1 in promoting tumor cell migration and sustaining mesenchymal-like cell morphology involves the upregulation of LEF1 and SNAI2." (PMID 23677615, 2013). "Despite these various studies indicating a regulatory role of IGF2BPs, in particular IGF2BP1, in directing the migration and invasive potential of tumor-derived cells in vitro, it remains elusive whether IGF2BPs also regulate tumor cell dissemination in vivo." (PMID 23677615, 2013). "However, in view of the multitude of descriptive studies indicating elevated expression of IGF2BP1/3 to correlate with tumor aggressiveness, their role in cancer cells remains poorly understood." (PMID 23677615, 2013). "Accordingly, IGF2BP1 knockdown causes MET-like (mesenchymal-epithelial-transition) morphological changes, enhances the formation of cell–cell contacts and reduces cell migration in various mesenchymal-like tumor-derived cells." (PMID 23677615, 2013). "Members of the let-7 family play a major role in cell differentiation and are considered to act as tumor suppressors by silencing numerous genes that encode oncogenic proteins including HMGA2, insulin-like growth factor 2-binding protein 1 (IGF2BP1), RAS and c-MYC." (PMID 21853155, 2011). "Therefore, IGF2BP1 might be a potential target for tumor diagnosis and anti-tumor therapeutic strategies." (PMID 40584294, 2025). "Collectively, IGF2BP1 could promote epithelial–mesenchymal transition as well as migration and invasion potentials of tumor cells by mediating m6A methylation; hence, the m6A/IGF2BP1 axis is beneficial for triggering tumor metastasis." (PMID 40584294, 2025). "Furthermore, efforts are needed to further clarify more in-depth and specific molecular mechanisms of IGF2BP1 in various tumors, including its binding mode with target mRNAs, its regulation of downstream signaling pathways, and its dynamic changes during tumor progression." (PMID 40584294, 2025). "Interestingly, a positive feedback loop of regulation was seen in the case of β-catenin and c-MYC, where in lung adenocarcinoma, the circular RNA circXPO1 binds IGF2BP1 and enhances the stability of β-catenin mRNA, driving Wnt/β-catenin activation, tumor growth, and poor clinical outcomes." (PMID 41516083, 2025). "Additionally, IGF2BP1 induces tumor metastasis by activating the ZIC2/PAK4/AKT/MMP2 axis." (PMID 40823087, 2025). "Additionally, the finding observed decreased apoptosis of HCC cells when co-cultured with CD8+ T cells, further suggesting that IGF2BP1 may contribute to the immune escape by modulating the HCC tumor microenvironment." (PMID 39606242, 2024). "Overall, it is proposed that IGF2BP1 acts as a phase-separated protein driving the formation of m6A mRNA-stabilized MLOs during tumorigenesis, and future anti-tumor therapy may target these IGF2BP1 condensates through inhibiting IGF2BP1 LLPS or dissolving them." (PMID 39239525, 2024). "The activation of the MIF - (CD74+CXCR4) axis indicates that IGF2BP1-overexpressing tumor cells may facilitate immune evasion through this pathway, consequently undermining anti-tumor immune responses and adversely impacting patient prognosis in immunotherapy contexts." (PMID 39512352, 2024). "Importantly, IGF2BP1 depletion impairs tumor growth, indicating that inhibition may have therapeutic potential in cancer cells." (PMID 39426983, 2024). "Our preliminary results confirmed the impact of IGF2BP1 on the clinical prognosis of HCC patients and the CD8+ T infiltration immune microenvironment, indicating that IGF2BP1 could potentially control the anti-tumor immunity of CD8+ T cells within the HCC microenvironment." (PMID 39606242, 2024).
tumor (continued). "For instance, IGF2BP1 could post-transcriptionally regulate the expression of some essential genes required for the control of tumor cell proliferation, invasion, and chemo-resistance, and was associated with a poor overall survival and metastasis in various types of human cancers." (PMID 37415734, 2023). "Also, IGF2BP1-R452K mutant significantly diminished the effect of PRMT3-OE on tumor growth." (PMID 37024475, 2023). "However, the regulatory mechanisms of m6A reader IGF2BP1 involved in ccRCC tumor energy metabolism are currently unknown." (PMID 36691477, 2023). "However, little was known about the tumor immune evasion regulated by IGF2BP1 in NSCLC." (PMID 36672208, 2023). "However, since IGF2BP1 is an oncofetal protein, questions about the physiological relevance of the reported interactions between IGF2BP1 and non-tumor viruses, primarily investigated in tumor-derived or embryonic cell lines, needs to be addressed by further analyses." (PMID 37515119, 2023). "However, IGF2BP1 has also been found to play a tumor-suppressive role in multiple cancers." (PMID 37554271, 2023). "Moreover, overexpressed IGF2BP1 completely abolished the inhibition of tumor evasion elicited by circCRIM1 overexpression, suggesting that IGF2BP1 may be a critical interacting protein of circCRIM1." (PMID 36672208, 2023). "Additionally, IGF2BP1 has been designated an oncofetal protein due to its space-time specific expression pattern: it is predominantly expressed in embryonic development and suppressed in most adult tissues but re-expressed in multiple tumor types." (PMID 37644505, 2023). "This emphasizes the broad impact which IGF2BP1 might have on tumor-promoting pathways." (PMID 35565249, 2022). "Positive correlations between higher levels of IGF2BP1-3 and C1, C2 and C6 infiltrates suggests that IGF2BPs may have a tumor promoter role, as patients belonging to those immune infiltrates subtypes had worse survival characterized with higher proliferation rate and enriched with TGFβ." (PMID 36686749, 2022). "This study revealed that the PADI2/MEK1/ERK/IGF2BP1 pathway could promote the characteristics of carcinogenic tumor cells in EC, and the combination of specific PADI2 and MEK1 inhibitors might provide a novel therapeutic target site for the treatment of the MEK inhibitor-resistant EC patients." (PMID 36371254, 2022). "Finally, the oncofetal IGF2BP1 gene that promotes tumor expression was also overexpressed." (PMID 36430456, 2022). "Nevertheless, our study stresses that IGF2BP1 immunohistochemistry has the potential to help not only defining a diagnosis but also to identify early dedifferentiation in areas of solid histoarchitecture in case of WDTC or even PDTC to prevent underestimation of tumor severity." (PMID 32719445, 2021). "However, it has also been reported that IGF2BP1 downregulation can promote tumor progression." (PMID 34692544, 2021). "The conserved target mRNA of IGF2BP1 encodes serum response factor (SRF), a highly conserved and widely expressed transcription factor that participates in cellular properties such as tumour cell growth and migration in a signal- and cytoskeleton-dependent manner." (PMID 34794452, 2021). "This study identifies exonic circular circPTPRA as a new tumor suppressor that inhibits cancer progression through endogenous blocking the recognition of IGF2BP1 to m6A-modified RNAs, indicating that circPTPRA may serve as an exploitable therapeutic target for patients with BC." (PMID 33853613, 2021). "Moreover, SRF/IGF2BP1-driven gene expression may also enhance a stem-like tumor cell phenotype, as supported by the recently reported role of SRF in promoting pluripotency and various studies indicating IGF2BPs to sustain stem-like cell properties." (PMID 30371874, 2019).
tumor (continued). "The expected similarities and conservation of SRF’s and IGF2BP1’s roles in modulating tumor cell properties suggested that the post-transcriptional regulator IGF2BP1 synergizes with the transcriptional regulator SRF in promoting an ‘aggressive’ tumor cell phenotype." (PMID 30371874, 2019). "Although the origin of difference between oncogenic and tumor-suppressive roles is unclear, the apparently contradictory functions of IGF2BP1 may result from tumor cells arrived from different origins or conditions with different responses to IGF2BP1 expression." (PMID 29954406, 2018). "In addition, we highlighted genes that may be common drivers of adenocarcinomas specifically, such as IGF2BP1, which suggests a possible link between embryonic development and tumor subtype." (PMID 28787442, 2017). "Hence, it remained contradictory whether IGF2BP1 promotes mesenchymal-like properties of tumor cells and modulates their migration in a largely cell context independent manner." (PMID 23677615, 2013). "Notably, IGF2BP1-controlled LEF1 expression could be validated by loss- as well as gain-of-function analyses and was observed in all mesenchymal-like tumor-derived cells analyzed in this study." (PMID 23677615, 2013). "To assess IGF2BP1’s role in tumor growth and immune evasion in vivo, we used ID8 cells—a syngeneic murine model of HGSC with CRISPR-Cas9-mediated knockout of Trp5336—that retain Igf2bp1-driven immune evasion in vitro." (PMID 41444249, 2025). "Multispectral imaging (MSI) of an independent HGSC-tissue microarray (TMA) further confirmed that higher IGF2BP1 expression correlated with reduced CTL infiltration and greater T cell to tumor cell distance." (PMID 41444249, 2025). "Among the top 100 deregulated genes, Wnt-associated genes such as LGR5, DKK1, and NKD1, as well as the HB-related genes DUSP9, DLK1, PEG3, PEG10, IGF2BP1, and IGF2BP2 were consistently upregulated in tumor samples." (PMID 40968384, 2025). "The present study identified circSLC22A3 as a new tumor suppressor that inhibited ESCC progression through both the circSLC22A3/ miR-19b-3p/ TRAK2 and circSLC22A3/ IGF2BP1/ ACSBG1 axes." (PMID 40448098, 2025). "BTYNB disrupted IGF2BP1–mRNA binding and induced leukemic differentiation; more recently, IGF2BP1 blockade reduced YAP1 signaling and tumor growth, strengthening the case for the druggability of reader–RNA interfaces." (PMID 41280938, 2025). "In colorectal cancer, for example, IGF2BP1 promotes G1/S transition by stabilizing E2F1 transcripts and modulates tumor-derived extracellular vesicle content, contributing to treatment resistance." (PMID 41210679, 2025). "Therefore, IGF2BP1 might be a promising target for anti-tumor therapy." (PMID 40584294, 2025). "In cervical cancer, exosome-derived miR-1323 from cancer-associated fibroblasts downregulates PABPN1, which then recruits IGF2BP1 to stabilize GSK-3β mRNA, activating Wnt/β-catenin signaling and promoting tumor progression and radio resistance." (PMID 41516083, 2025). "This creates a positive feedback loop involving EP300, CMTM6, IGF2BP1, and EP300 (mRNA), which strengthens tumor stemness and promotes drug resistance in PDAC." (PMID 40356985, 2025). "Microarray analysis revealed that IGF2BP1 and IGF2BP2, both known to stabilize mRNA, were upregulated in HBL tumor samples, and their expression correlated with ADAM32 levels." (PMID 40507253, 2025). "This analysis identified IGF2BP1 as having the highest prognostic value for HNSC patients, and it also exhibited differential expression between tumor and normal tissues in meRIP-seq analysis." (PMID 39512352, 2024). "IGF2BP1, HNRNPA2B1, FTO, WTAP promote the EC progression, but METTL3, METTL14, YTHDF2 work as tumor suppressors in EC." (PMID 39582531, 2024). "This loop reinforces tumor stemness by stabilizing MYC and EP300 mRNAs via IGF2BP1‐mediated m6A modification." (PMID 39488785, 2024).